LIMD1 (LIM domain containing 1)
Diseases named in the same sentence as LIMD1 in open-access papers (continued):
Sharing a sentence is not in itself a finding about the gene and the disease.
colon cancer (1 paper, 2020). "We can state that only Ajuba and not its closely related LIM domain family members WTIP and LIMD1 are significantly increased in colon cancer compared to adjacent non-tumor tissues." (PMID 32679899, 2020).
dysplasia (1 paper, 2018). A usually neoplastic transformation of the cell, associated with altered architectural tissue patterns. "In contrast, LIMD1 and CDC25A showed high nuclear expressions in both basal/parabasal (80.06%, 82.76% respectively) and spinous layers (80.06%, 74.71%) of normal epithelium with significant loss of their expression during development of dysplasia (63.88%, 52.78%) and HNSCC (43.42%, 47.37%)." (PMID 29672635, 2018).
endometrial cancer (1 paper, 2021). Primary or metastatic malignant neoplasm involving the endometrium (mucous membrane that lines the endometrial cavity). "Similarly, Zyxin, LIMD1 and TRIP6 mutations are linked with endometrial cancer." (PMID 33808029, 2021).
heart failure (1 paper, 2021). Inability of the heart to pump blood at an adequate rate to meet tissue metabolic requirements. "Future studies to examine LIMD1 and its function in cardiac fibroblasts in combination with SKI’s role in fibroblast physiology may lead to the generation of data that could be exploited for selective therapeutic targeting in cardiac fibrosis and heart failure." (PMID 33847835, 2021).
latent infection (1 paper, 2018). "As to its role in the setting of EBV latent infection, we show that LIMD1 interacts with TRAF6, a crucial mediator of LMP1 signal transduction." (PMID 29464072, 2018).
lentivirus infection (1 paper, 2020). Virus diseases caused by the Lentivirus genus. "By performing lentivirus infection and screening, we successfully constructed cell lines overexpressing LIMD1 (A549-LIMD1, H1299-LIMD1) and their respective controls (A549-vec and H1299-vec)." (PMID 32754438, 2020).
Myocardial fibrosis (1 paper, 2025). "In this study, we observed that the upregulation of LIMD1 significantly attenuated myocardial fibrosis in HF mice." (PMID 39937832, 2025).
oral cavity cancer (1 paper, 2010). A primary or metastatic malignant neoplasm involving the oral cavity. "Multivariate analysis showed that LIMD1 molecular alterations (P, 0.03; HR, 4.5; CI, 1.1-17.8) along with tobacco addiction (P, 0.05; HR, 4.5; CI, 0.96-20.8) in absence of HPV (P, 0.05; HR, 0.28; CI, 0.08-0.99) were significant predictor for poor survival of patients with oral cavity cancer." (PMID 20226061, 2010).
ovarian carcinoma (1 paper, 2021). A malignant neoplasm originating from the surface ovarian epithelium. "In fact, S233 phosphorylation of LIMD1 has been identified by high throughput profiling assays in many other cancers, including breast and ovarian cancers and pancreatic ductal adenocarcinoma, with or without stresses." (PMID 33869018, 2021).
tumor (23 papers, 2010 to 2025). "Loss of LIMD1 and its multiple tumour suppressive functions lead to alterations and disruption of these key regulatory pathways, driving cellular transformation and cancer progression." (PMID 34764236, 2021). "We show that LIMD1 expression is significantly downregulated in NSCLC, and have identified LIMD1-associated tumor-infiltrating immune cells (TILs), and molecular and immune signatures in this setting." (PMID 33869018, 2021). "Compare to frequent deletion and methylation, mutation of LIMD1 was increased during tumor progression (P = 0.007)." (PMID 20226061, 2010). "Staining of these tumours with markers for cell proliferation (Ki67) and apoptosis (cleaved caspase-3), revealed that PF-477736 selectivity inhibits proliferation in LIMD1-deficient lung xenografts and increases apoptosis within these tumours, in agreement with our in vitro data." (PMID 34764236, 2021). "Our study has identified a novel therapeutic strategy based on LIMD1 status, which exploits the loss of this tumour suppressor, offering the potential for targeted treatment for this large cancer-patient population and significantly reduce disease burden worldwide." (PMID 34764236, 2021). "We have also identified a subgroup of tumor-infiltrating lymphocytes, especially neutrophils, whose tumor infiltration levels significantly correlate with LIMD1 level in both LUAD and LUSC." (PMID 33869018, 2021). "LIMD1+/+ tumours were unaffected by PF-477736 treatment in vivo, however we observed a significant decrease in tumour growth in the LIMD1−/− tumours upon treatment." (PMID 34764236, 2021). "Further, LIMD1 significantly correlates with tumor-infiltrating regulatory T cells (Treg) and negatively correlates with tumor-infiltrating MDSCs in LUAD, and also significantly correlates with tumor-infiltrating macrophages and B cells in LUSC." (PMID 33869018, 2021). "To explore the potential mechanisms responsible for LIMD1-mediated tumor suppression, we first analyzed genome-wide LIMD1 interaction network in STRING, BioGRID, and GeneMANIA." (PMID 33869018, 2021). "LIMD1 plays a regulatory role in many biological functions in tumor cells and acts as a tumor suppressor." (PMID 32754438, 2020). "LIMD1's multiple tumour‐suppressive functions and its discrimination between binding partners are likely to be regulated by different signalling cascades, with multiple phosphorylation events on LIMD1 having already been identified." (PMID 29930174, 2018). "In vivo, inhibition of hypoxia‐driven LIMD1 expression results in larger and more vascularised xenograft tumours." (PMID 29930174, 2018). "In summary, these findings reveal the existence of a previously uncharacterised tumour‐suppressive, negative regulatory feedback loop in which LIMD1 facilitates HIF degradation in hypoxia." (PMID 29930174, 2018). "In a xenograft model for tumorigenesis, ablation of the hypoxic inducibility of LIMD1 expression and subsequent loss of hypoxic HIF‐1α protein regulation caused increased tumour vasculature and growth." (PMID 29930174, 2018). "Our recent work has shown that LIMD1 is a critical effector of microRNA (miRNA)‐mediated gene silencing, a process generally considered to be a global tumour‐suppressive mechanism." (PMID 29930174, 2018). "As a scaffold protein, LIMD1 exerts multiple tumour‐suppressive functions depending on its binding partners." (PMID 29930174, 2018). "We identified that the tumour suppressor LIMD1, which facilitates efficient degradation of the transcriptional regulator of hypoxia, is itself a HIF target gene." (PMID 29930174, 2018). "After a structural analysis of both binding partners, we suggest that this novel interface is responsible for PHD2 interaction with the LIMD1 tumor suppressor." (PMID 26754054, 2016). "Additionally, LIMD1 is recognized as a prognostic marker for survival in gastric cancer, where it inhibits tumor progression by restraining YAP1 activation." (PMID 39937832, 2025).
tumor (continued). "Previous studies have predominantly explored the role of LIMD1 in immunity and tumor progression." (PMID 39937832, 2025). "In this respect, treatment with MRS1220 reduced the transcripts of 29 genes that could tentatively favor the tumor phenotype; three targets that promote chemoresistance, LIMD1, TRIB2, and TGFB1, were distinguished." (PMID 38794149, 2024). "Several previous studies have suggested the suppressor role of Limd1 in tumor diseases." (PMID 37009626, 2023). "Thus, LIMD1, known as a tumor suppressor in several tumors such as lung, gastric, and breast cancers, oppositely acts as a tumor promoter in viral hematomalignancies." (PMID 34771613, 2021). "LIMD1 was previously identified as a tumor suppressor in lung cancer, but their detailed interaction in this setting remains unclear." (PMID 33869018, 2021). "In summary, this meta-analysis indicates that LIMD1, as a tumor suppressor in lung cancer, is significantly downregulated in NSCLC, and could serve as a prognosis marker for LUAD but not for LUSC." (PMID 33869018, 2021). "The results of CCK-8 assay, colony formation assay, and EdU assay suggested that the reverse regulation of LIMD1 could partially abolish the affection of miR-550a-5p on tumor proliferation in LUAD." (PMID 33194664, 2020). "Since LIMD1 is a tumor suppressor gene in LUAD, we speculated that miR-550a-5p might exert a cancer-promoting effect by directly targeting LIMD1." (PMID 33194664, 2020). "A large number of previous studies have suggested that LIMD1 functions as a tumor suppressor." (PMID 33194664, 2020). "In terms of molecular mechanism, LIMD1 could participate in cellular processes and pathways through its scaffold function, meaning that the tumor-suppressive function of LIMD1 is likely to be regulated by different signal cascades." (PMID 33194664, 2020). "Compared to adjacent tissues, relative expression of LIMD1 mRNA was low expressed in tumor tissues." (PMID 33194664, 2020). "Therefore, through experiments in the current research, directly targeting the 3′-UTR of LIMD1 is the reason that miR-550a-5p functions as a tumor promoter." (PMID 33194664, 2020). "In this study, we have identified that a reduction in LIMD1 expression (through ablation of the hypoxic responsiveness of LIMD1 promoter) is sufficient to cause a HIF‐mediated pathological transcriptome and phenotype in the form of increased tumour size and vasculature." (PMID 29930174, 2018). "The paradox roles of LIMD1 may depend on its post-translational modifications; cell-cycle-dependent phosphorylation may play a role in its function as a tumor suppressor." (PMID 29464072, 2018). "To complement the bioinformatic analysis of patient tumours, we performed cell line‐based in vitro analysis of the gene expression changes that occur in a primary lung epithelial cell background following a reduction in LIMD1 expression." (PMID 29930174, 2018). "LIMD1 (LIM domain-containing protein 1) is considered as a tumor suppressor, being deregulated in many cancers to include hematological malignancies; however, very little is known about the underlying mechanisms of its deregulation and its roles in carcinogenesis." (PMID 29464072, 2018). "The observation that the resistance of tumor cells to chemotherapy correlates with the overexpression of transport proteins, including LIMD1, has prompted efforts to develop agents with the ability to inhibit LIMD1-mediated drug transport." (PMID 25013501, 2014). "The reduced level of LIMD1 in tumor cells might destabilize the pRB-E2F interaction and chromatin remodeling complex, resulting deregulation of cell cycle." (PMID 20226061, 2010). "However, during progression of the tumor comparable frequencies of these alterations were seen, suggesting the deletion and methylation of LIMD1 as early events in this tumorigenesis." (PMID 20226061, 2010).
tumor (continued). "However, LIM-domain proteins belonging to the related CRP family have been described as potent tumor suppressor genes and, most importantly, the related LIMD1 gene has been recently reported to display functional properties reminiscent of tumor antagonizing genes." (PMID 21646684, 2011). "Unlike methylation and deletion, significant association of LIMD1 mutation with tumor progression indicates that mutation might have some additive effect in inactivation of this gene." (PMID 20226061, 2010). "Hypoxic induction of LIMD1 expression results in increased HIF‐α protein degradation, inhibiting HIF‐1 target gene expression, tumour growth and vascularisation." (PMID 29930174, 2018). "Our data indicates that compared to normal epithelium, low basal/ parabasal expression of RBSP3 was maintained, while the high expression of LIMD1 and CDC25A were lost during tumour development due to genetic/ epigenetic alterations." (PMID 29672635, 2018). "Here, we analyzed the mRNA levels of AJUBA and two other AJUBA family members, WTIP and LIMD1, in ESCC tumor tissues and in their matched adjacent non-tumor tissues." (PMID 27172796, 2016). "Specifically, the LIMD1 gene responds to hypoxia through an HIF1-α response element in its promoter and, as a protein, acts as a scaffold to stabilize the PHD2/VHL/HIF-1α degradation complex, in this sense working as a tumor suppressor." (PMID 38794149, 2024). "However, the mRNA levels of WTIP and LIMD1 were not dysregulated in tumor tissues." (PMID 27172796, 2016). "Taken together, these results show that LIMD1 is upregulated in EBV latency and plays an oncogenic role rather than that of a tumor suppressor." (PMID 29464072, 2018). "Transmission of the basal- like signature RBSP3 occurred during tumorigenesis, but the signature of LIMD1 and CDC25A was altered and hence not transmitted during development and progression of tumours." (PMID 29672635, 2018). "However, the basal- like signature of LIMD1 and CDC25A was not transmitted during tumour development." (PMID 29672635, 2018).
cancer (14 papers, 2010 to 2025). A tumor composed of atypical neoplastic, often pleomorphic cells that invade other tissues. "The third and last new variant was found in LIMD1, a gene with reports of involvement in cellular processes and the progression of diseases such as cancer." (PMID 38543725, 2024). "We have identified a novel drug tool with significant preclinical characterisation that serves as an excellent candidate to explore and define LIMD1-deficient cancers as a new therapeutic subgroup of critical unmet need." (PMID 34764236, 2021). "LIMD1 is a multi-functional protein involved in stabilization of pRB-E2F interaction, miRNA silencing, Hippo signaling, etc. and is highly altered in different cancers." (PMID 29672635, 2018). "Thus, it can be concluded that LIMD1 is a susceptible gene for HNSCC development and its alterations, alone or with RB1 alterations acts as an important prognostic marker in this cancer." (PMID 20226061, 2010). "LATS2, MCC, DCC, RHOB, TRIM13, LIMD1, and GPC3 also strongly and positively regulated gene down-expression in cancer." (PMID 33580150, 2021). "However, the pathophysiological link between this mechanistic role of LIMD1 within the PHD‐LIMD1‐VHL HIF regulatory complex and cancer is unknown." (PMID 29930174, 2018).
hematological malignancies (2 papers, 2018 to 2021). "In contrast, our recent studies have shown that LIMD1 plays a pro-oncogenic role in hematological malignancies in association with the oncogenic transcription factor interferon regulatory factor 4 (IRF4)." (PMID 33869018, 2021). "We have previously shown that LIMD1 expression correlates with IRF4 in hematological malignancies, suggesting that LIMD1 may be transcriptionally regulated by IRF4." (PMID 29464072, 2018).
adenocarcinoma (1 paper, 2021). A common cancer characterized by the presence of malignant glandular cells. "We have already shown selectivity of PF-477736 against LIMD1−/− A549 cells, a NSCLC adenocarcinoma cell line." (PMID 34764236, 2021).
cardiovascular disease (1 paper, 2023). "In cardiovascular disease, Limd1 has been reported to be functionally closely related to cardiac fibroblasts." (PMID 37009626, 2023).
LIMD1 also shares sentences with these, for which no sentence is quoted: head and neck squamous cell carcinoma (2 papers); non-small cell lung carcinoma (2); acute myeloid leukemia (1); blood cancers (1); clear-cell renal cell carcinoma (1); diffuse large B-cell lymphoma (1); glioblastoma (1); glioma (1); leukemia (1); lung adenoma (1); lung squamous cell carcinoma (1); lymphoid neoplasm (1); myeloma (1); neuroblastoma (1); pancreatic ductal adenocarcinoma (1); squamous cell carcinoma (1); stomach cancer (1); thalassemia (1); type 2 diabetes (1); uterine carcinosarcoma (1); uterine corpus endometrial carcinoma (1).